PDCD4 (programmed cell death 4)
Diseases named in the same sentence as PDCD4 in open-access papers (continued):
Sharing a sentence is not in itself a finding about the gene and the disease.
glioma (continued). "Based on the TCGA data, we confirmed that AKT2, but not AKT1 or AKT3, interacts with PDCD4, thus leading to the suppression of PDCD4 in glioma cells." (PMID 33304903, 2020). "Inhibition of PDCD4, and consequently release of eIF4A and activation of translation, decreases apoptosis, promotes cell cycle arrest at G0/G1, and stimulates glioma stem cell proliferation as well as GBM cell invasiveness." (PMID 31795417, 2019). "They demonstrated that blocking the methylation in glioma cells using the DNA methyltransferase inhibitor 5-aza-2 deoxycytidine restored PDCD4 expression and inhibited the proliferation of the cells." (PMID 31075975, 2019). "By applying lentivirual based vectors in U251 glioma cells lines, we probed anti-oncogenic proteins of PDCD4, RECK and PTEN at both protein and mRNA levels for their expression." (PMID 26284486, 2015). "Moreover, the inhibition of hnRNPC can reduce the expression of miRNA-21 in gliomas and promote the expression of PDCD4, thus inhibiting metastasis." (PMID 40469294, 2025). "Notably, miR-21 overexpression is inversely correlated with PDCD4 expression, hindering apoptosis in glioma cells." (PMID 39459612, 2024). "Further, qRT-PCR and Western blot analysis showed CLEC19A overexpression could reduce the expression levels of PI3K, VEGFα, MMP2, and NF-κB and increase PTEN, TIMP3, RECK, and PDCD4 expression levels in glioma cell lines." (PMID 38167030, 2024). "Targeting STAT1 through FDA approved drugs could possibly rescue the oncogenic effect of FAT1 in glioma mediated by FAT1 -PDCD4 axis." (PMID 37476290, 2023). "MiRNA-21 exerts its oncogenic function in gliomas through its post-transcriptional targets and downstream signal pathways: PDCD4, phosphatase and tensin homolog (PTEN), tumour protein 63 (TP63), tropomyosin 1 (TPM1), and tissue inhibitor of metalloproteases 3 (TIMP3)." (PMID 33610185, 2021). "We next tested whether over-expression of PDCD4 can suppress glioma growth in vivo using a xenograft BALB/c nude mice tumor model." (PMID 33304903, 2020). "Additionally, depletion of levels of PDCD4 promoted angiogenic activity of glioma cells via the VEGF-STAT3 pathway." (PMID 33304903, 2020). "Among the 16 cancer types (originating in the glial cells, thyroid, lung, liver, pancreas, head and neck, stomach, colon and rectum, urethra, bladder, ureters and renal pelvis, prostate, cervix, endometrium, and skin), PDCD4 was significantly down-regulated in glioma." (PMID 33304903, 2020). "Additionally, our in vivo data suggested that enhancing expression of PDCD4 can block tumorigenesis and prolong overall survival, supporting the necessity to develop potential drugs for up-regulating PDCD4 in glioma patients in the clinics." (PMID 33304903, 2020). "However, the functions of PDCD4 and the mechanism by which PDCD4 is down-regulated in human glioma cells remains to be completely elucidated." (PMID 33304903, 2020). "To determine whether PDCD4 contributes to tumor suppression in glioma cells, we depleted the expression levels of PDCD4 using two different shRNAs." (PMID 33304903, 2020). "In addition to relying on caspases to regulate apoptosis, found that miR-21 can also affect the apoptosis of glioma cells through targeted regulation of the tumour suppressor gene PDCD4." (PMID 31293827, 2019). "Using RT-PCR, western blot and immunocytochemistry, they found that PDCD4 was decreased in gliomas." (PMID 31795417, 2019). "Furthermore, enhanced expression of PDCD4 decreases tumorigenic capacity of glioma stem cells in vivo as demonstrated in a GBM xenograft mouse model." (PMID 31795417, 2019). "Moreover, PDCD4 as a tumor suppressor was previously reported to be suppressed by PRC2 complex via increasing the level of H3K27me3 at its promoter in glioma." (PMID 30519392, 2018). "Therefore, the findings with regard to BRD4-HOTAIR-β-catenin/PDCD4-mediated tumor development provide new insight into the complexity of glioma." (PMID 28187439, 2017).
glioma (continued). "Moreover, miR-155, miR-181a/b and miR-410 may participate in the molecular mechanism of high-grade glioma by interaction PDCD4, WNT5A, MET, and EGFR." (PMID 35646622, 2022). "MicroRNA-21 derived from T. gondii infected microglial cells promoted the growth of U86 glioma cells through suppressing antitumoral genes (FoxO1, PTEN, and PDCD4)." (PMID 37818043, 2023). "The oncogenic effect of miRNA-21 in human glioma cells is implemented through the suppression of such tumor suppressor genes as TAp63, HNRPK, JMY, TOPORS, RECK, TP53BP2, TIMP3, PDCD4, and TGFBR2/3." (PMID 37033545, 2023). "We have earlier shown that knock down of FAT1 led to increased PDCD4 level and repression of AP1 activity in glioma cells." (PMID 37476290, 2023). "For example, exosomes containing miR-21 produced an effective downregulation of the PDCD4 and RECK genes in glioma cell lines." (PMID 35629138, 2022). "A study of engineered exosomes containing miRNA (particularly miR-21) show they effectively downregulated target genes PDCD4 and RECK of the miR-21 in glioma cell lines." (PMID 35205721, 2022). "Latest reports have shown that these miRNAs by regulation PDCD4, WNT5A, MET, and EGFR also serves certain biological function in the progression of various human tumors including glioma." (PMID 35646622, 2022). "Here, we present evidence that AKT2, but not AKT1 or AKT3, interacts with PDCD4 leading to its suppression in glioma cells, and is consistent with the inverse relationship between mRNA levels of AKT2 and PDCD4 observed in the TCGA data analysis." (PMID 33304903, 2020). "MiR-21 is also known to contribute to glioma's resistance to chemotherapy by targeting tumor suppressor genes such as FBXO11 and PDCD4." (PMID 26473373, 2015). "miR-21 plays a role in the regulation of cell proliferation, apoptosis and tumor invasiveness by targeting PTEN, PDCD4, and RECK, and has been shown to be involved in gliomas carcinogenesis process." (PMID 22642976, 2012). "Interestingly, the combination of miR-21 with programmed cell death 4 (PDCD4) can inhibit PDCD4 expression, which inhibits apoptosis and promotes glioma invasive activities via the promotion of AKT and p70S6K pathway activation." (PMID 40469294, 2025). "Also, our in vitro evidence has shown that the expression level of PDCD4 and PTEN increased in glioma cells after CLEC19A overexpression." (PMID 38167030, 2024). "The western blot analysis indicated that knockdown of PDCD4 in glioma cells enhanced p-STAT3 levels, but not p-ERK or p-FAK1." (PMID 33304903, 2020). "Taken together, these data suggest that AKT2, but not AKT1 or AKT3, interacts with and suppresses PDCD4 in the glioma cells." (PMID 33304903, 2020). "Moreover, we found that PDCD4 regulates the expression of IL-5, CCL-5, VEGF, and CXCL10 in glioma cells, which provides a therapeutic opportunity to block these cytokines." (PMID 33304903, 2020). "Consequently, the expression of circulating miR-155, miR-410, and miR-181a/b and its putative gene-targets PDCD4, WNT5A, MET, and EGFR had a strong inverse relation in high-grade glioma, thereby suggesting that the potential roles of miR-155, miR-410, and miR-181a/b in oncogenesis of glioma tumors." (PMID 35646622, 2022).
gastric cancer (37 papers, 2010 to 2025). A primary or metastatic malignant neoplasm involving the stomach. "Overexpressed and knocked down of miRNA-208a in MKN45, HGC-27 and AGS gastric cancer lines caused suppression- or increased expression of PDCD4 protein respectively." (PMID 35847932, 2022). "Association between TWIST1 or PDCD4 expression and clinicopathological features in gastric cancer patients." (PMID 25144746, 2014). "Here, we explored the regulation of EMT-associated proteins and PDCD4 expression in gastric cancer tissue and CagA activation of TWIST1 expression and inhibition of E-cadherin and PDCD4 expression in gastric cancer cells." (PMID 25144746, 2014). "As well, decreased PDCD4 expression was inversely associated with changed TWIST1 expression during gastric cancer (p = 0.035)." (PMID 25144746, 2014). "According to some studies, the deletion and mutation of KLF6 and PDCD4 were associated with gastric cancer and colon carcinogenesis, since the downregulation of these cancer suppressor genes were found to promote over-proliferation of cells." (PMID 23825654, 2013). "PDCD4 expression was negatively associated with miR-21 levels in gastric cancer." (PMID 28423589, 2017). "Association between expression of Twist1 or PDCD4 in gastric cancer." (PMID 25144746, 2014). "As well, loss of PDCD4 expression is associated with malignant transformation in gastric cancer." (PMID 25144746, 2014). "Another research indicated that HIF1α-activated miR-17-5p promotes tumor growth and metastasis of gastric cancer by repressing PDCD4." (PMID 38485986, 2024). "Our findings highlighted that the expression of both G0S2 and PDCD4 were inhibited in gastric cancer tissues while compared with the normal tissues." (PMID 36366842, 2023). "Our research characterized the regulation of circSNTB2/miR-6938-5p/G0S2 and PDCD4 pathways and their role in gastric cancer." (PMID 36366842, 2023). "PDCD4 has also been shown to be involved in microglia activation, gastric cancer growth, apoptosis of placental trophoblasts via the miRNA-21-PDCD4 pathway, and cerebral ischemia/reperfusion injury." (PMID 36826085, 2023). "The investigators used a miRNA array to examine two gastric cancer tissues and found that miRNA-23b-3p, miRNA-17-5p and miRNA-93 inversely correlated with PDCD4 expression and were therefore candidate regulators of the tumour suppressor." (PMID 35847932, 2022). "Overexpressing miRNA-17-5p in MKN-45 gastric cancer cells increased proliferation and migration, and decreased PDCD4 expression, whereas silencing miRNA-17-5p had the opposite effect." (PMID 35847932, 2022). "Overall, it was concluded that NR2F2-AS1 acts as a tumour suppressor in gastric cancer by sponging miRNA-320b, alleviating possible suppression of PDCD4 by this microRNA." (PMID 35847932, 2022). "NR2F2-AS1 can down-regulate the expression of PDCD4 and inhibit the development of gastric cancer through competitive binding with miR-320b, it can also inhibit miR-494 methylation to regulate oral squamous cell carcinoma cells proliferation." (PMID 35571063, 2022). "Transfection of mimics of these miRNAs into gastric cancer AGS cells containing a PDCD4 3’ UTR reporter plasmid reduce fluorescence, indicating direct binding to the 3’ UTR and suppression of translation." (PMID 35847932, 2022). "This has also been seen in immortalised gastric cancer cell lines, where overexpression of miRNA-21 resulted in decreased expression of PDCD4 and increased migration and invasion." (PMID 35847932, 2022). "The up-regulation of the miR-23a, inhibited the gastric cancer cell apoptosis by down-regulating the Programmed Cell Death 4 (PDCD4)." (PMID 30577536, 2018). "In summary, this study not only uncovered the critical roles of miR-23a/b as oncomiRs in gastric cancer but also explored the molecular mechanisms through which miR-23a/b contributed to gastric cancer progression and identified PDCD4 as a direct target gene." (PMID 28981115, 2017).
gastric cancer (continued). "In contrast to the upregulated expression levels of miR-23a/b, PDCD4 protein levels were dramatically downregulated and inversely correlated with miR-23a/b in gastric cancer tissues." (PMID 28981115, 2017). "In this study, we observed that PDCD4 was consistently reduced in gastric cancer tissues compared with normal adjacent tissues." (PMID 28981115, 2017). "We measured the expression pattern of PDCD4 in the same 10 pairs of gastric cancer tissues and normal adjacent tissues." (PMID 28981115, 2017). "The correlation between miR-23a/b and PDCD4 was further examined by evaluating PDCD4 expression levels in two human gastric cancer cell lines, MKN-45 and AGS, after overexpression or knockdown of miR-23a/b." (PMID 28981115, 2017). "In summary, as miR-23a/b and PDCD4 had opposite expression patterns and biological functions in gastric cancer cells, it is quite possible that miR-23a/b suppress apoptosis in gastric cancer cells by silencing PDCD4." (PMID 28981115, 2017). "We then investigated the molecular mechanisms through which miR-23a/b contribute to gastric cancer and identified programmed cell death 4 (PDCD4) as a direct target gene of miR-23a/b." (PMID 28981115, 2017). "Taken together, this study highlights an important role for miR-23a/b as oncomiRs in gastric cancer through the inhibition of PDCD4 translation." (PMID 28981115, 2017). "The disparity between PDCD4 protein and mRNA levels in gastric cancer tissues suggested a post-transcriptional mechanism involved in the regulation of PDCD4." (PMID 27021515, 2016). "This disparity between PDCD4 protein and mRNA expression in gastric cancer tissues strongly suggests that a post-transcriptional mechanism is involved in PDCD4 regulation." (PMID 27634902, 2016). "Subsequently, we evaluated the biological effects of miR-208a-3p and PDCD4 on the growth of gastric cancer cells in a gastric cancer xenograft mouse model." (PMID 27634902, 2016). "Because miRNAs play important roles in post-transcriptional regulation, it is quite likely that miRNAs regulate PDCD4 expression in human gastric cancer." (PMID 27634902, 2016). "We demonstrated that the repression of PDCD4 through miR-93 suppressed the apoptosis of gastric cancer cells." (PMID 27021515, 2016). "Taken as a whole, this study delineates a novel regulatory network employing miR-93 and PDCD4 to fine-tune apoptosis in gastric cancer cells." (PMID 27021515, 2016). "The potential role of miR-93 as an oncomiR of gastric cancer through PDCD4 targeting in apoptosis has been experimentally validated." (PMID 27021515, 2016). "In gastric cancer, PDCD4 regulates apoptosis through the downregulation of FLICE-inhibiting protein (FLIP), a negative regulator of apoptosis." (PMID 27021515, 2016). "The PDCD4 expression levels were shown to decrease in a number of different human tumors, including glioblastoma and cancers of the stomach, pancreas, colon, lung, prostate, ovary and liver." (PMID 27634902, 2016). "Distinctly lower expression levels of PDCD4 were observed in gastric cancer tissues compared to matched adjacent normal tissues by immunohistochemistry." (PMID 27634902, 2016). "We next analyzed the biological consequences of the miR-93-driven repression of PDCD4 expression in gastric cancer cells." (PMID 27021515, 2016). "We further experimentally validated PDCD4 as the direct target of miR-93 by evaluating PDCD4 expression in gastric cancer cells after the overexpression or knockdown of miR-93." (PMID 27021515, 2016). "We evaluated the biological effects of miR-93 and PDCD4 on the growth of gastric cancer cells in a gastric cancer xenograft mouse model." (PMID 27021515, 2016). "PDCD4 was reported to intensively promote cell apoptosis, and play an important role in mediating the sensitivity of gastric cancer cells to TRAIL-induced apoptosis through FLIP suppression." (PMID 27634902, 2016).
gastric cancer (continued). "In the present study, we observed that overexpressing miR-93 inhibits apoptosis in gastric cancer cells, and reducing PDCD4 expression mimics miR-93 induction." (PMID 27021515, 2016). "Simultaneously, we showed that PDCD4 protein was frequently downregulated in gastric cancer tissues, and we identified discordance between the PDCD4 protein and mRNA levels in human gastric cancer tissues." (PMID 27634902, 2016). "Lost expression of PDCD4 protein has been identified in many different human cancers, such as cancers of stomach, pancreas, colon, lung, prostate, ovary and liver." (PMID 27634902, 2016). "Taken together, the findings of the present study indicated the oncogenic role of miR-93 in gastric cancer tumorigenesis through targeting PDCD4, particularly in apoptosis." (PMID 27021515, 2016). "In summary, these results demonstrated that miR-93 directly binds to the 3′-UTR of the PDCD4 mRNA transcript and inhibits PDCD4 translation in gastric cancer cells." (PMID 27021515, 2016). "Programmed cell death 4 (PDCD4), as a tumor suppressor gene, is frequently reduced in a variety of tumors, including gastric cancer." (PMID 27021515, 2016). "The correlation between miR-208a-3p and PDCD4 was examined by evaluating PDCD4 expression in human gastric cancer cell lines (MKN45, HGC-27 and AGS) after overexpression or knockdown of miR-208a-3p." (PMID 27634902, 2016). "By knocking down or overexpressing miR-208a-3p in gastric cancer cells, we validated that miR-208a-3p directly inhibited PDCD4 translation." (PMID 27634902, 2016). "To investigate the clinical relevance of PDCD4 in gastric cancer, we first examined PDCD4 expression in human gastric cancer tissues." (PMID 27634902, 2016). "As an important post-transcriptional target of microRNA (miR) miR-21, PDCD4 is related to tumor progression and prognosis in human lung, colorectal, breast and gastric cancer." (PMID 25144746, 2014). "We provide some insight into the molecular network of gastric cancer induced by H. pylori infection, and supply a theoretical basis for PDCD4 as a biological target for diagnosis or treatment of cancer." (PMID 25144746, 2014). "In summary, we demonstrate that H. pylori CagA induce TWIST1 expression and EMT in gastric cancer cells by regulating PDCD4." (PMID 25144746, 2014). "For instance, miR-21 enhanced the cell proliferation by targeting PDCD4 in cervical cancer HeLa cells and gastric cancer." (PMID 24112539, 2013). "Upregulation of miR-499-5p via STAT3 signaling pathway could increase gastric cancer cell proliferation and invasion by targeting PDCD4." (PMID 35402235, 2022). "Interestingly, we identified discordance between PDCD4 protein and mRNA levels in human gastric cancer tissues, suggesting that a post-transcriptional regulatory mechanism is involved in PDCD4 repression." (PMID 28981115, 2017). "PDCD4 protein levels were consistently reduced in gastric cancer tissues." (PMID 28981115, 2017). "The results indicated that combined miR-23a/b overexpression may be involved in the progression of gastric cancer through co-targeting tumor suppressor PDCD4 in this malignancy." (PMID 28981115, 2017). "Furthermore, we identified potential target genes of miR-23a/b and found that miR-23a/b inhibit the apoptosis of gastric cancer cells by directly targeting an important tumor suppressor, programmed cell death 4 (PDCD4)." (PMID 28981115, 2017). "We also provided evidence that PDCD4 functions as an essential pro-apoptotic factor in gastric cancer: silencing PDCD4 expression in gastric cancer cells through siRNA inhibits apoptosis, whereas overexpressing PDCD4 has a remarkable effect in promoting cell apoptosis." (PMID 28981115, 2017). "Since miRNAs are generally thought to have an opposite expression pattern to that of their targets, we next investigated whether miR-23a/b expression was inversely correlated with PDCD4 expression in gastric cancer tissues." (PMID 28981115, 2017).